CRP (C-reactive protein)
Diseases named in the same sentence as CRP in open-access papers (continued):
Sharing a sentence is not in itself a finding about the gene and the disease.
malaria (continued). "Results demonstrated a higher mean CRP level in patients with severe malaria than in those with uncomplicated malaria (p: 0.001, SMD: 1.72, 95% CI: 0.41–3.04, I2: 96.3%, five studies)." (PMID 34764364, 2021). "A three-part differential hematology analyzer has the potential to not only trigger malaria diagnosis confirmation but also assess the severity of the infection when CRP is considered." (PMID 34565334, 2021). "Median CRP values were within the normal ranges in parasitic infections, while they were higher in malaria (97.20, IQR: 38.49–160.09), although they were significantly lower than those found for bacterial infections (p < 0.0001)." (PMID 34574070, 2021). "A pooled analysis using the fixed-effects model demonstrated a higher mean CRP level in patients with uncomplicated malaria than in healthy/febrile controls (p < 0.001, SMD: 1.49, 95% CI: 1.42–1.57, I2: 99.2%)." (PMID 34764364, 2021). "From 1024 children enrolled in the trial, we included a subset (n = 820) who had complete baseline and endline data for hemoglobin, ferritin, sTfR, malaria, CRP, and AGP at both baseline and endline." (PMID 35844700, 2021). "Sufficient plasma volume to measure CRP levels was available for 730 individuals: CRP levels of >20 mg/L were observed among 68/730 (9.3%) individuals, of whom 60 had positive malaria microscopy." (PMID 33647009, 2021). "The difference in the mean CRP level between asymptomatic malaria patients and febrile/healthy controls was estimated using 10 studies." (PMID 34764364, 2021). "Full blood count and C-reactive protein were exclusively requested at the hospital, while malaria rapid test was performed only at the health center." (PMID 33845920, 2021). "Results of the individual study demonstrated a higher mean CRP level in asymptomatic malaria patients than in febrile/healthy controls in all 10 studies." (PMID 34764364, 2021). "For the Micros-EMI-CRP, the inclusion of CRP in the flagging algorithm provided valuable information for malaria screening, increasing sensitivity beyond only the CBC data." (PMID 33228680, 2020). "TSAT< 11% performed well over a range of CRP concentrations, in children with both malaria and inflammation, and across populations." (PMID 32102669, 2020). "This study evaluated the usefulness of high-sensitivity CRP (hs-CRP) in malaria diagnosis and morbidity in a pediatric population in Ghana." (PMID 31089391, 2019). "The malaria pathway upregulates C-reactive protein and serum hepcidin, thereby reducing iron absorption." (PMID 31771607, 2019). "Women with malaria are more likely to have raised CRP and therefore, more likely to be misclassified as iron replete." (PMID 30231938, 2018). "Sensitivity, specificity, PPV and NPV of an increased CRP level for malaria were 99.3% (CI 96.2%-100%), 9.2% (CI 6.4%-12.8%), 31.7% (CI 27.4%-36.1%) and 97.0% (CI 84.2%-99.9%), respectively." (PMID 30080904, 2018). "The aim of this study was to evaluate the value of a semi-quantitative CRP test to predict clinical malaria among febrile children in a highly endemic area of Ghana." (PMID 30080904, 2018). "Almost all of the patients with a detectable parasitemia (267/270, 98.9%) and those with clinical malaria (144/145, 99.3%) had elevated CRP levels." (PMID 30080904, 2018). "C-Reactive Protein (CRP) has also been studied lately in patients with malaria in Africa and other parts of the world." (PMID 30080904, 2018). "Baseline samples were collected to measure hemoglobin levels, serum ferritin, vitamin B12, folate, C-reactive protein, alanine amino-transferase, the presence of malaria, HIV, and soil transmitted helminth infections." (PMID 30562390, 2018). "In the univariate analysis, elevated CRP levels were seen in patients with parasitemia and those with malaria." (PMID 30080904, 2018).
malaria (continued). "Whereas malaria parasites were detected in only a few patients (7.1%) with normal CRP levels (< 10mg/l), more than a half of patients with an increased CRP concentration (≥ 10 mg/l) were parasite positive (OR 14.5 [CI 4.4–47.6], p<0.001)." (PMID 30080904, 2018). "The adjusted OR of patients with a CRP > 10 mg/l for malaria was nine (adjusted OR 9.1 [CI 1.2–69.2], p = 0.034)." (PMID 30080904, 2018). "From our results, though CRP is elevated in parasitemia and in malaria, it lacks the ability to differentiate a Plasmodium spp." (PMID 30080904, 2018). "We excluded patients with a positive malaria RDT in this study as earlier studies have shown the inability of CRP/WBC to differentiate between malaria and bacterial infections despite tendencies of higher values in bacterial infections." (PMID 27935664, 2017). "In PSC, malaria had a weak relation (as a dichotomous variable) with sTfR ranging from 0.08 to 0.20, with CRP ranging from 0.17 to 0.28, and with AGP ranging from 0.12 to 0.24; in WRA, the relation of malaria with sTfR and the APPs ranged from 0.01 to 0.10." (PMID 28615256, 2017). "The rank correlations between malaria and CRP or AGP ranged from 0.12 to 0.27 in PSC and from 0.04 to 0.10 in WRA." (PMID 28615259, 2017). "Sixty percent of children had malaria parasites and CRP was raised in 89% of them, indicating that inflammation was present in most children." (PMID 28587263, 2017). "Patients with malaria 45/56 (80.4%), typhoid fever 12/13 (92.3%) and urinary tract infection 25/50 (50%) were observed to have elevated CRP levels of > 40mg/L but with WBC≤15 103cells/μL) and ANC≤10 103cells/μL)." (PMID 28451028, 2017). "The limited evidence from previous research studies conducted in Angola and Tanzania that investigated CRP levels among malaria patients also documented similar findings." (PMID 28451028, 2017). "Second, there are concerns about using CRP testing to detect bacterial infections in patients with malaria (malaria infection in itself leads to high levels of CRP and PCT)." (PMID 29059253, 2017). "Overall, elevated serum CRP and AGP, and a positive malaria test were associated with a higher Mead acid:AA ratio." (PMID 28705254, 2017). "The presence of a rash, unusual in malaria, normal levels of C-reactive protein and leukopaenia has been described more related to dengue fever than to malaria." (PMID 27230739, 2016). "A better understanding of plasma CRP concentrations in individuals in malaria endemic settings is needed to determine the potential use of CRP as a guide for antibiotics in febrile patients with negative malaria tests." (PMID 27386859, 2016). "The significantly high level of CRP observed among khat chewer malaria patients is an indication for presence of excess uric acid (UA) in the bloods of the chewers." (PMID 26173100, 2015). "An episode of malaria was predefined as current Plasmodium infection with an inflammatory response (axillary temperature ≥37.5°C or whole blood C-reactive protein concentration ≥8 mg/L) in children reported sick." (PMID 26088606, 2015). "This is the largest ever study to measure and compare procalcitonin and C-reactive protein levels in malaria endemic settings." (PMID 26558692, 2015). "The AUROC value for procalcitonin in discriminating between malaria and bacterial infections was 0.69 (95 % CI 0.64–0.74) and for CRP it was 0.54 (0.49–0.6)." (PMID 26558692, 2015). "Diagnosis is based on the existence of malaria parasites in peripheral blood smear that is done asexual forms (thin & thick smear Platelet count, CRP and ESR thick)." (PMID 26131347, 2015). "Most remarkably, Malaria group presented the highest levels of CRP and intestinal parasites the highest level of IL-12p70, IL-17A, and NO." (PMID 25309052, 2014). "Blood samples were collected and analysed for serum-ferritin (SF), C-reactive protein (CRP), haemoglobin and malaria-parasitaemia (MP)." (PMID 24644526, 2014).
malaria (continued). "The sensitivity and specificity of CRP>5 mg/L to discriminate malaria from dengue were of 0.995 (95%CI: 0.991–1) and 0.35 (95%CI 0.32–0.39), respectively." (PMID 24069477, 2013). "Few reports have been published about the values of CRP in malaria patients, and generally showed that it is elevated, as reported in a Zambian study." (PMID 24069477, 2013). "Of the inflammatory markers tested, CRP showed the highest sensitivity and specificity in the malaria patients." (PMID 23866258, 2013). "This however cannot be used alone since LDH and CRP has been found elevated in blood samples from all febrile travellers in a previous study, as well as in malaria cases." (PMID 23937856, 2013). "Five biomarkers showed the highest AUROC in all malaria patients compared to the control group: CRP (1.00), MPO (0.99), D-dimers (0.98), elastase-2 (0.98), and sICAM-1 (0.98)." (PMID 23866258, 2013). "We found unexpectedly low circulating CRP levels in a rural, lean, and apparently healthy Ghanaian population living under adverse environmental conditions in a malaria endemic area." (PMID 23922912, 2013). "The combination of travel history, fever prior to blood sampling, and CRP serum levels above or below 10.8 mg/l upon hospital admission, best discriminated between malaria patients and control persons." (PMID 23866258, 2013). "The current findings implicate that a CRP level above 155 mg/l predicts severe malaria with a sensitivity and specificity of 79% and 80%, respectively." (PMID 22221299, 2012). "CRP had a significantly better performance than either copeptin, sodium and lactate for prediction of severe malaria but its usefulness in clinical practice is probably limited." (PMID 22221299, 2012). "C-reactive protein (0.84 [95% CI 0.79-0.89]) had a significantly better performance as a biomarker for severe malaria than the other biomarkers." (PMID 22221299, 2012). "Finally, genetic variants of FCGR2A, an immunoglobulin G receptor, could be associated with an increased risk of malaria because of a significant reduction in its binding capacity for IgG and C reactive protein (CRP) and the consequent reduced phagocytosis of IgG and CRP opsonized structures." (PMID 22691414, 2012). "WPB-associated proteins Ang-2, vWF, and vWF propeptide were elevated in children with severe malaria compared to UM, as were inflammatory biomarkers CRP, PCT, and sTREM-1 (p<0.01)." (PMID 21364762, 2011). "In fact, SAA along with CRP has been proven to be valuable in assessing the severity of malaria and particularly as a prognostic tool in following response to treatments." (PMID 22028888, 2011). "Previous works explored biomarkers for malaria infection, particularly serum amyloid A (SAA) and C reactive protein (CRP) were identified as important malaria biomarkers." (PMID 22028888, 2011). "In this study, we assessed the utility of PCT and CRP to differentiate viral from invasive bacterial pneumonia in children in Manhiça, a rural malaria-endemic area of Mozambique with high HIV prevalence." (PMID 20976241, 2010). "These cytokines stimulate the hepatic synthesis of acute phase inflammatory proteins, including CRP, which increase in malaria." (PMID 21144084, 2010). "We have assessed the usefulness of PCT and CRP to differentiate viral from invasive bacterial pneumonia in rural Africa, where malaria, HIV and other co-morbidities are common." (PMID 20976241, 2010). "Although our results show restrictions on the use of PCT and CRP in a malaria-endemic context, presence of P. falciparum can rapidly be assessed with a RDT." (PMID 20976241, 2010). "CRP binds with a higher affinity to the receptor expressed by the R allele, which might have a competitive effect on the binding of the previously shown malaria protective immunoglobulins (Ig) G1 and IgG3, thereby interfering with the protection against malaria." (PMID 19545442, 2009). "Sixty per cent of severely anaemic children had malaria parasites in their blood; CRP was raised in 89%." (PMID 19946096, 2009).
malaria (continued). "In future studies there is a need to study both unstimulated and plasma levels stimulated by malaria in relation to CRP genotypes in Africa." (PMID 19545442, 2009). "This study demonstrated that the Malaria/CRP Duo RDT could be performed well by the majority of VMWs." (PMID 40340660, 2025). "The cut-off for a positive CRP test result with the Malaria/CRP Duo was 20 mg/L, a threshold that emphasises sensitivity over specificity, which may be most appropriate for use by VMWs in remote Cambodian villages." (PMID 40340660, 2025). "The chances of having a high level of CRP in the serum were slightly increased by malaria." (PMID 40277833, 2025). "C-reactive protein (CRP), a human pro-inflammatory marker, has been investigated as a biomarker to differentiate bacterial from non-bacterial infection in febrile participants, with the combined use of rapid tests for CRP and malaria being recommended for consideration in febrile case management." (PMID 39177882, 2025). "Between June 2022, and May 2023, a total of 2,425 febrile patients were assessed with either a Malaria/CRP Duo or Dengue Duo RDT." (PMID 40340660, 2025). "VMWs provided with the Malaria/CRP Duo RDT were satisfied with the ease of its use." (PMID 40340660, 2025). "The Dengue Duo RDT proved more challenging to use and interpret than the Malaria/CRP RDT." (PMID 40340660, 2025). "All participants underwent routine blood investigations (hemogram, liver, and renal function tests), tropical serology (dengue, leptospirosis, malaria, chikungunya, and scrub typhus), and measurement of inflammatory markers, including C-reactive protein and serum ferritin." (PMID 41567885, 2025). "A CRP RDT (within a combo-RDT or alone) that functions similarly to the CRP component of the Malaria/CRP Duo could be easily integrated into the routine practice of VMWs and could aid the management of febrile illness in the community." (PMID 40340660, 2025). "It has been noted that CRP is a helpful biomarker for differentiating between dengue and malaria." (PMID 39997008, 2025). "There was dissatisfaction from patients regarding the blood volume required for the dengue test (110 μl vs 15 μl for malaria/CRP), which was seen by some patients as potentially harmful and may affect the future acceptability of the test." (PMID 38166839, 2024). "Additionally, elevated CRP has been observed in individuals with both complicated and uncomplicated malaria and can be used as a biomarker for monitoring of the malaria severity." (PMID 39066199, 2024). "Moreover, CRP levels correlated with parasite density at day one and they were significantly higher in the severe malaria group (p < 0.0001)." (PMID 37889376, 2024). "Unexpectedly, however, one-third of malaria RDT–positive cases had CRP levels <20 mg/L." (PMID 37490743, 2023). "Malaria has been shown to be a confounding factor for CRP analysis in developing countries." (PMID 37478118, 2023). "CRP levels differed between malaria-positive and malaria-negative patients (malaria is expected to be associated with elevated CRP levels)." (PMID 37490743, 2023). "This may be because the DPP necessitated an extra waiting time of 5 min (20–25 min in total) compared with the Dengue and Malaria/CRP Duos (15–20 min in total)." (PMID 37317948, 2023). "Our study was unable to find a CRP value beyond which we could safely exclude either bacterial infection or malaria, as the highest CRP values found in both conditions were very similar (both > 300mg/L)." (PMID 37478118, 2023). "Using these cut-offs, positive and negative fraction tables were drawn for malaria and bacterial infection which demonstrated that at these cut-offs, CRP had PPVs of 68.75% and 85.00% for malaria and bacterial infection respectively, with NPVs of 94.74% and 89.05% respectively." (PMID 37478118, 2023).
malaria (continued). "If a child presented with a haemoglobin level under 8 g/L, a thrombocyte count under 200 × 10E9/L and a CRP level over 100 mg/L, the odds of a positive malaria PCR sample was 4.8-fold (95% confidence interval [CI], 2.2–10.4) compared to children not fulfilling these criteria." (PMID 37087435, 2023). "This implies that CRP can perform adequately for excluding malaria in this setting." (PMID 37478118, 2023). "Most patients with malaria (36/50) and bacterial infection (33/49) had CRP > 40mg/L." (PMID 37478118, 2023). "However, the study also is not without limitations which include the low number of children with asymptomatic malaria or with acute inflammation (CRP)." (PMID 37974246, 2023). "Approaches have included correcting ferritin concentrations through equations that adjust for inflammation (CRP and/or alpha-1 glycoprotein) and the presence of malaria, or by excluding participants with elevated CRP on the assumption that inflammation increases ferritin." (PMID 36079755, 2022). "Alterations of inflammatory markers have been investigated to predict malaria infection and follow-up on malaria severity, such as using plasma lactate, copeptin, neopterin, and c-reactive protein (CRP) as these molecules are simple laboratory-based parameters." (PMID 36141662, 2022). "Actual antimicrobial prescriptions given to the children were compared with those that could be given based on combined CRP-malaria testing." (PMID 36536340, 2022). "One study indicated that using PCT with a cut-off at 0.9 ng/mL in combination with CRP increased the correctness of identifying patients with severe malaria on admission than using CRP with other laboratory parameters such as copeptin, sodium, or sodium lactate." (PMID 36141662, 2022). "Mean maternal age was ∼25 y, 17.8% were anemic, 13.1% were HIV-positive, 22.4% tested positive for malaria, 41.7% had elevated plasma CRP concentrations, 13.8% had elevated plasma AGP concentrations, and 40.1% had inflammation-corrected plasma selenium concentrations <1.0 μmol/L." (PMID 35317414, 2022). "Sensitivity analyses were conducted to assess associations between ID and malaria after (a) adjusting ferritin levels for CRP and AGP, but not concurrent malaria infection; and (b) excluding women with malaria parasitaemia at enrolment." (PMID 35619134, 2022). "Malaria and other infections were prevalent, with almost two-thirds of the children testing positive for malaria parasites at enrollment, and only 32% free of inflammation, based on normal CRP and AGP levels." (PMID 35829783, 2022). "Although these CRP concentrations are lower than those seen in children with acute clinical malaria (median 7.1, IQR 5.5 - 8.0), they may be indicative of a low level inflammatory state." (PMID 35154104, 2022). "The results of the meta-analysis supported that the elevated levels of CRP may help in the prognosis of disease severity among patients infected with malaria." (PMID 34764364, 2021). "The CRP parameter showed the most significant difference between malaria and dengue samples." (PMID 34565334, 2021). "While a negative malaria RDT would then support the prescription of antibiotics in a febrile patient with high CRP, a positive malaria RDT test would still leave the healthcare provider with their clinical judgement, as one cannot rule out with all certainty a concomitant bacterial infection." (PMID 34574070, 2021). "A high CRP level with other routine laboratory parameters could help differentiate patients with uncomplicated malaria from those with asymptomatic malaria." (PMID 34764364, 2021). "This study investigated whether C-reactive protein (CRP) can be used as a marker for the early detection and monitoring of malaria severity." (PMID 34764364, 2021). "In addition, the Spearman’s rank correlation coefficients between age and CRP value in each subgroup of malaria species were calculated." (PMID 34565334, 2021).